RNU6-1068P (RNA, U6 small nuclear 1068, pseudogene)
Gene: Small nuclear RNA gene on chromosome 12 (101,411,357 to 101,411,459, forward strand). Ensembl gene ENSG00000222890.
Homologues: Orthologues: chimpanzee U6 (100% identical), macaque U6 (97% identical). Paralogues in human: RNU6-38P (88% identical), RNU6-664P (87% identical), RNU6-1011P (86% identical), RNU6-1145P (86% identical), RNU6-28P (86% identical), RNU6-698P (86% identical), RNU6-842P (86% identical), RNU6-1124P (85% identical), RNU6-140P (85% identical), RNU6-144P (85% identical), RNU6-25P (85% identical), RNU6-29P (85% identical), and 1288 more.